MYCN (MYCN proto-oncogene, bHLH transcription factor)
Diseases named in the same sentence as MYCN in open-access papers (continued):
Sharing a sentence is not in itself a finding about the gene and the disease.
neuroblastoma (continued). "With this in mind, we designed a cell-based screen utilizing an isogenically derived set of neuroblastoma cells with either high-level expression of wild-type MYCN or with genetically modified, stabilized MYCN (lacking the CPD target phosphorylation residues, T58 and S62)." (PMID 27438153, 2016). "Together, these gene expression data from three independent experiments containing a total of 986 human neuroblastoma samples reveal a significant negative correlation between hASH1 and genes involved in neuron differentiation in neuroblastoma that is independent of MYCN function." (PMID 28066180, 2016). "Hence, DpC and Dp44mT generally demonstrated greater activity in neuroblastoma cells with MYCN amplification when compared to those without this alteration." (PMID 27678372, 2016). "Interestingly, this prognostic value seems to be restricted to stage 4 neuroblastoma patients and to be independent of MYCN amplification status, which alone is a known negative prognostic factor." (PMID 27829219, 2016). "However, the relationship between EYA1 and MYCN in the context of neuroblastoma has not been explored." (PMID 28713571, 2016). "Notably, abrogation of N-Myc function also significantly inhibited glutamine consumption and glutamate production, arguing that N-Myc promotes glutamine deamidation in MYCN-amplified neuroblastoma cells in part through GLS2 activation." (PMID 26528759, 2015). "This discrepancy between literature and our data could be explained by the fact that our integrative approach identifies MYCN-targeting miRNAs in neuroblastoma using gene expression data from MYCN non-amplified primary tumors." (PMID 25294817, 2015). "The observed sensitivity is also comparable to those of multiple myeloma and MYCN-amplified neuroblastoma cell lines, reported to be potentially JQ1-sensitive tumor types, and substantially higher than those of lung adenocarcinoma and MYCN-WT neuroblastoma cell lines." (PMID 26284497, 2015). "We have demonstrated that methotrexate uptake in neuroblastoma cells is mediated principally by the reduced folate carrier (RFC; SLC19A1), that SLC19A1 and MYCN expression are highly correlated in both patient tumors and cell lines, and that SLC19A1 is a direct transcriptional target of N-Myc." (PMID 25860940, 2015). "Interestingly, investigation of β-catenin expression in neuroblastoma tumour sections without MYCN amplification revealed particularly high expression in high-risk tumours." (PMID 25266063, 2015). "The ODC gene is found upstream of MYCN and since MYCN amplification is seen in 30% of neuroblastoma, ODC overexpression is common in NB patients and correlates with poor outcomes." (PMID 25415050, 2015). "Overall, the 12 MYCN-targeting miRNAs in neuroblastoma, show significantly more downregulation during MYCN-driven tumor development, compared to non-targeting miRNAs, as indicated by a shift of the cumulative distribution of the π-values (−log10 p-value *Δ slope) to more negative values." (PMID 25294817, 2015). "Moreover, elevated GLS2 expression is significantly elevated in MYCN-amplified neuroblastomas in comparison with non-amplified ones, correlating with unfavorable patient survival." (PMID 26528759, 2015). "ChIP assays confirmed that binding of MYCN could be detected in the MYCN-amplified neuroblastoma cell lines NB19 and LA-N-1, whereas it was absent in the non-MYCN-amplified SHSY5Y cell line." (PMID 25477524, 2015). "Hence, our findings further clarify the role of miRNAs in the regulation of MYCN in neuroblastoma and describe a negative feedback loop from MYCN to its targeting miRNAs." (PMID 25294817, 2015).
neuroblastoma (continued). "The same group performed gene expression studies in MYCN nonamplified neuroblastomas, and identified a 14-gene signature consisting of both inflammatory and tumor cell genes that could predict disease progression." (PMID 26729169, 2015). "Additionally, the PI3K/mTOR inhibitor PI103 induced time- and concentration-dependent inhibition of cell growth in both MYCN and non-MYCN amplified neuroblastoma cell lines." (PMID 25134527, 2014). "MYCN amplification this time, however, was seen in homogeneously staining regions rather than in the double minute pattern, which raised the possibility of metachronous neuroblastoma, rather than metastatic progression." (PMID 24810334, 2014). "MYCN status, i.e., amplified vs. non-amplified, was one of the very first biomarkers in oncology to discriminate aggressive from less aggressive or even favorable clinical courses of neuroblastoma." (PMID 25161957, 2014). "However, the combined effects of PAX3 inhibition and chemotherapeutic drugs were tested only in MYCN-non-amplified neuroblastoma cells in this study, and MYCN is frequently amplified in advanced stage neuroblastomas with chemotherapy resistance." (PMID 24188742, 2014). "To address whether MAX expression could affect neuroblastoma by activating a differentiation pathway, we have analyzed a dataset of MYCN non-amplified neuroblastoma cells SH-SY5Y subjected to a differentiation protocol." (PMID 24349289, 2013). "Similarly, I-BET726 anti-tumor activity was observed in both non-MYCN-amplified and MYCN-amplified neuroblastoma models." (PMID 24009722, 2013). "Indeed, MYCN up-regulates miR-17-92 cluster and one of the effects is a down-regulation of DKK3 a gene with tumor suppressor function involved in Wnt pathway and having a significance value in neuroblastoma prognosis." (PMID 23482921, 2013). "Of further notice, LIN28B, a negative regulator of the let-7 family of miRNAs targeting MYCN mRNA, was amplified in rare neuroblastoma cases and more recently transgenic mice overexpressing LIN28B in the developing sympathetic nervous tissue were shown to develop neuroblastoma." (PMID 23308108, 2013). "It is still unknown if MYCN directly or indirectly regulates this miRNA but it is clear that miR-542-5p expression correlates with TRKA expression both in vivo and in vitro thus playing a role in neuroblastoma outcome." (PMID 23482921, 2013). "Notably, our four-gene signature shows predictive value in neuroblastoma patients with stage 4 disease and without MYCN amplification." (PMID 24348903, 2013). "Our analyses also point that this gene may be used as a candidate predictor for positive clinical outcomes of MYCN non-amplified neuroblastoma patients." (PMID 24349289, 2013). "The p110β isoform has also been implicated in various malignancies, but we could not detect any difference between stage 1–2 and stage 4 neuroblastoma p110β protein levels, although slightly higher levels were detected in MYCN amplified tumors." (PMID 23597230, 2013). "Concerning neuroblastoma, consistent data indicate that MNA cells are strikingly sensitive to death induced by MDM2-antagonist, while cell growth inhibition might be the preferential outcome in MYCN single copy neuroblastoma." (PMID 23091802, 2012). "To explore the possibility that MYCN might be directly binding to the TIMP2 promoter and directly repressing transcription, we examined previously published genome-wide MYCN binding site data for neuroblastoma." (PMID 22662276, 2012). "Interestingly, all these genes were highly up-regulated (p-value<0.01) in aggressive neuroblastoma tumors (stage 4, with MYCN amplification) in comparison to non-aggressive tumors (stage 1 without MYCN amplification)." (PMID 23251412, 2012).
neuroblastoma (continued). "Coherently, although MYCN overexpression may induce apoptosis in cells from the nervous system, this was not so frequently reported in neuroblastoma cells." (PMID 23091802, 2012). "Early studies found that several c-MYC target genes were expressed in some neuroblastoma cell lines with MYCN amplification, but not all, suggesting that other cell specific factors may be important." (PMID 23226679, 2012). "Notably, amplification of the MYCN transcription factor is one of the most powerful adverse prognostic factors in neuroblastoma and we have previously demonstrated that PTPRD is expressed at significantly lower levels in MYCN amplified neuroblastoma relative to non-MYCN amplified tumors." (PMID 22305495, 2012). "Interestingly, the prognostic value of low p27KIP1 expression in neuroblastoma, independent of MYCN status had previously been demonstrated." (PMID 23226679, 2012). "The expression levels of the control genes (MYCN, MEIS1 and ALK) were, in all three cases, when compared to all healthy samples, healthy nervous system samples and healthy peripheral nervous system samples, highly and statistically significantly elevated in neuroblastoma." (PMID 20444257, 2010). "To verify that MYCN could interact with the B-MYB promoter region encompassing the putative E-BOXes in human neuroblastoma cells in vivo, we carried out Chromatin-IP analysis, which confirmed that MYCN binds to the B-MYB promoter only in a MYCN-amplified cell line." (PMID 21304178, 2010). "In SH-EP neuroblastoma cells, transfection assays followed by Western blot showed no MYCN expression in presence of the control plasmid (pcDNA/GW40/lacZ), weak but detectable translation from p-MYCN, whereas a very high amount of protein was obtained with p-MYCNΔ1b." (PMID 20017904, 2009). "This pattern of metabolite values is not seen in neuroblastomas, however, 5 of the 7 tumours were MYCN non-amplified and it has been established in cell lines that phosphocholine/glycerophosphocholine is high in MYCN amplified but not MYCN non-amplified tumours." (PMID 19208232, 2009). "We used primers spanning exon 2 to visualize by reverse transcriptase PCR whether or not both transcripts are present in MYCN-amplified IMR-32 neuroblastoma cells." (PMID 19615087, 2009). "In favor of a cellular context factor, we observed that promoter constructs from the PTMA gene, which is highly expressed in stage 4s NA and MYCN amplified tumors, showed a strong activation in N-type but not S-type neuroblastoma cell lines despite similar MYCN protein levels (unpublished data)." (PMID 18851746, 2008). "Because increased activity of MYCN in stage 4s-NA or c-MYC in stage 4-NA tumors should both result in high expression of shared target genes compared to localized-NA neuroblastomas, we analyzed known direct MYCN/c-MYC target genes, namely MDM2, DKC1, and PTMA, in neuroblastoma subtypes." (PMID 18851746, 2008). "Notably, knock down of miR-17-5p by antagomir sharply inhibits the in vitro and in vivo tumorigenesis of MYCN-amplified LAN-5 cells, suggesting that miR-17-5p is a key oncogenic factor in both MYCN-amplified and not-amplified neuroblastoma." (PMID 18493594, 2008). "Our results suggest preferential use of glycolysis for energy production and MYCN expression may be independent markers of neuroblastoma malignancy in vitro if not in vivo." (PMID 18789162, 2008). "However, we observed that miR-106b is not upmodulated in MYCN-amplified neuroblastoma cells (data not shown), thus suggesting that in neuroblastoma miR-106b is not involved in p21 regulation." (PMID 18493594, 2008).
neuroblastoma (continued). "While we acknowledge this lack of correlation may not reflect in vivo bioenergetic capabilities of neuroblastoma, we propose that MYCN expression and an upregulated Warburg effect may be independent markers of neuroblastoma malignancy." (PMID 18789162, 2008). "Finally, we evaluated the expression of MYCN, miR-17-5p and p21 mRNA in freshly dissected primary neuroblastomas, including MYCN-amplified and not-amplified tumors." (PMID 18493594, 2008). "We investigated whether use of glycolysis for energy production even in the presence of oxygen (known as the Warburg effect) varied between neuroblastoma cell lines with or without MYCN amplification (a key indicator of poor disease outcome in neuroblastoma)." (PMID 18789162, 2008). "Further, despite compelling evidence for MYC and RAS cooperation in vitro and in vivo to promote tumourigenesis, activation of RAS signal transduction does not constitute a preferred secondary pathway in neuroblastomas with MYCN deregulation in either human tumors or murine models." (PMID 16822308, 2006). "More importantly, a higher MK level was strongly correlated with poor prognostic factors: over 1 year of age (P=0.0299), MYCN amplification (P<0.0001), low TrkA expression (P=0.0005), nonmass screening, sporadic neuroblastomas (P<0.0001), and diploidy/tetraploidy (P=0.0007)." (PMID 12771916, 2003). "By analyzing single‐cell transcriptomic data from 5 neuroblastoma patients with MYCN amplification and 7 patients without MYCN amplification (GSE21840), and applying machine learning approaches, we identified five candidate pathogenic genes potentially associated with MYCN amplification." (PMID 40600620, 2025). "Furthermore, we propose a strategy for the targeted disruption of the KLHL37-N-Myc complex, and suggest that RTA-408, an inhibitor of KLHL37, may serve as a potential pharmacological approach for the treatment of patients with MYCN-amplified neuroblastoma." (PMID 40493396, 2025). "We show that of the total number of cases, an average of 90% of the samples classified as neuroblastoma, while 66% also achieved confident classification into the three NB subclasses: “MYCN-type”, “ALT/TERT TMM positive” and “TMM negative”." (PMID 40713849, 2025). "As these dependency datasets continue to grow, with an emphasis on expanding the representation of nonamplified neuroblastoma lines, we should be able to determine whether this vulnerability is unique or more pronounced in MYCN-amplified compared to MYCN–wild-type neuroblastoma." (PMID 38820154, 2024). "MYCN activates canonical MYC targets involved in ribosome biogenesis, protein synthesis and represses neuronal differentiation genes to drive oncogenesis in neuroblastoma (NB)." (PMID 37781575, 2023). "Finally, the interaction of MYCN with the transcription factor HAND2 (heart and neural crest derivatives-expressed protein 2), that permits MYCN chromosome accessibility and enhancer binding in neuroblastoma, was abolished by the Aurora-A inhibitor alisertib, disrupting tumour growth." (PMID 37414143, 2023). "One could argue the tumourigenic impact of the Aurora-A and -B kinases is exacerbated by MYCN-amplification, an assertion supported by work using the dual Aurora-A/B kinase inhibitor CCT137690 that solely demonstrated efficacy in MYCN-amplified neuroblastoma cell lines and in vivo." (PMID 37414143, 2023). "The univariate Cox analysis demonstrated that NB patients with age at diagnosis >318 days, International Neuroblastoma Staging System (INSS) stage 4, DNA diploidy, MYCN amplification status, and children oncology group (COG) high-risk group had a relatively poor prognosis." (PMID 37746942, 2023).
neuroblastoma (continued). "Interestingly, we detected five neuroblastomas with amplified MYCN in the early-MRCA class, and, remarkably, all of these patients survived until the end of the observation periods (1,447–4,177 days), in contrast to the poor survival of patients with MYCN-amplified tumors in the late-MRCA group." (PMID 36973454, 2023). "However, as MYCN amplification accounts for only 50% of all high-risk neuroblastoma cases, CCL2 may be a potential factor associated with increased risk in tumors that are not MYCN-amplified." (PMID 37964011, 2023). "Moreover, analysis of neuroblastoma patient data revealed that high expression of CPT1C is associated with poor prognosis, although it is not clear whether MYCN has a role in its upregulation." (PMID 36077650, 2022). "Therefore, we speculated that MYCN non-amplified neuroblastoma cells would be more resistant to VLX600." (PMID 35805002, 2022). "Moreover, the ROC analysis in the TARGET, E-MTAB-161, E-MTAB-8248, E-TABM-38, GSE16476 and GSE49710 datasets showed that the nomogram model could predict the overall survival of MYCN nonamplified paediatric neuroblastoma." (PMID 35655142, 2022). "Together with other findings showing that iron chelators could induce cell death regardless of MYCN status and the fact that MYCN/C-MYC is still unable to be targeted, MYCN is an important clinical marker, but may not be a necessary direct target for the treatment of neuroblastoma." (PMID 35805002, 2022). "Based on age at diagnosis, MYCN amplification status, International Neuroblastoma Staging System (INSS) stage, histopathology and tumor cell ploidy, NB patients are stratified into low-, intermediate-, and high-risk groups according to the 2007 COG risk system." (PMID 36530992, 2022). "Since, E2F1 and E2F3 were prognostic makers of neuroblastoma independent of MYCN amplification and age of diagnosis, the combinations of E2F1 or E2F3 with MYCN amplification or age of diagnosis could achieve better prognostic effects in pediatric neuroblastoma patients." (PMID 35764946, 2022). "MYCN and NTRK1 exert opposing functions in neuroblastoma (NB)." (PMID 34771457, 2021). "Hence, we hypothesized that pharmacologically induced differentiation of neuroblastoma cells with retinoids depends on reprogramming of the adrenergic CRC, leading to rapid down-regulation of MYCN expression, even in the context of massive MYCN gene amplification." (PMID 34669465, 2021). "However, because MYCN amplification and 1p LOH are not observed in approximately half of all high-risk neuroblastoma patients, it has been suggested that genetic aberrations other than MYCN amplification and 1p LOH are involved in the development and progression of the disease." (PMID 34796286, 2021). "However, it was observed that MYCN is a transcriptional regulator of MRE11, RAD50, and NBS1, and the MRN complex contributes to the control of DNA damage levels compatible with tumor cell survival, so that high MRE11 expression is related to reduced overall survival in primary human neuroblastoma." (PMID 34201502, 2021). "The discovery of rearrangements inducing the overexpression of TERT in the absence of MYCN-amplification or the mechanisms of the alternative lengthening of telomeres (ALT), often due to mutation or deletion of ATRX, identified telomere maintenance as a feature defining high-risk neuroblastomas." (PMID 34442335, 2021). "We also observed genes previously associated with 17q21-ter gain in neuroblastoma, such as TBX226, PPMD127, JMJD614, and BIRC528 being differentially expressed in 17q21-ter gain patients, whereas MYCN mRNA expression associated with MYCN-amplification but not 17q21-ter gain." (PMID 33767157, 2021).